INS (insulin)
Diseases named in the same sentence as INS in open-access papers (continued):
Sharing a sentence is not in itself a finding about the gene and the disease.
diabetes (continued). "For example, one of the participants represented a project the KT Platform supported with an embedded KT expert to co-create a strategy to implement a new therapy (basal bolus insulin therapy) to improve in-hospital management of individuals with diabetes." (PMID 30971263, 2019). "Pioglitazone, the only thiazolidinedione drug in clinical practice is under scrutiny due to reported adverse effects, it’s unique insulin sensitising action provides rationale to remain as a therapeutic option for managing type 2 diabetes mellitus (T2DM)." (PMID 30926892, 2019). "For example: a guy with diabetes, he quit smoking but then his sugar levels went up and he needed to start with insulin." (PMID 31175194, 2019). "Diabetes is a chronic disease resulting from either failure of insulin secretion, insulin action, or both." (PMID 31645652, 2019). "Studies support the involvement of mitochondria in the pathology of diabetes, including its dysfunction, and the production of damaging free reactive oxidative species, as well as decreased insulin secretion and increased resistance." (PMID 31781665, 2019). "The insulin signaling pathway and Type 2 diabetes mellitus pathways were most significantly enriched by the targets of hsa-miR-221-3p and were selected for closer investigation." (PMID 31222113, 2019). "The associated factors included female gender, longer duration of diabetes, non-insulin treatment, complications including neuropathy, nephropathy, and foot ulcers, and admission due to infected foot ulcers, HHS, and hypoglycaemic coma." (PMID 31131177, 2019). "In this way they introduced an intermediate time-scale between fast glucose-insulin equilibration and slow diabetes evolution." (PMID 31600232, 2019). "Vaspin (visceral adipose tissue-derived serpin, serpinA12) is a member of the serine protease inhibitor family of serpins, whose expression shows the highest values when plasma insulin levels and obesity peak, while they are lower in the presence of diabetes." (PMID 30754657, 2019). "In this study, we investigated the causal relationship between uPA and T2DM by using wild-type and uPA knockout (uPA-/-) mice, indexing the diabetes-induced rate, insulin resistance, and insulin secretion." (PMID 31756973, 2019). "Treatment with fucoidan increased serum insulin level, delayed the onset and decreased the development of diabetes in NOD mice." (PMID 31889967, 2019). "Taking into account the world diagnostic standard, it seems important to emphasize the role of insulin homeostasis in annual diagnostics, not only in patients with disorders in the carbohydrate metabolism or with a history of diabetes in the family." (PMID 31428627, 2019). "Transplantation of stem cell-derived insulin producing cells (IPCs) has been proposed as an alternative to islet transplantation for the treatment of diabetes mellitus." (PMID 30926860, 2019). "Insulin-dependent diabetes mellitus, or type 1 diabetes (T1D), is an autoimmune condition in which insulin-producing pancreatic islet cells undergo immune-mediated destruction." (PMID 31244856, 2019). "Episodes of hypoglycemia are frequent in patients with diabetes treated with insulin or sulphonylureas." (PMID 31349701, 2019). "Several studies demonstrated that the administration of α-LA at a dose of 600 mg improved insulin sensitivity in patients with type 2 diabetes mellitus and cognitive functions in patients with Alzheimer's Disease." (PMID 31635029, 2019). "Insulin-dependent diabetes mellitus is characterized by the auto-immune, T-cell mediated destruction of insulin-producing beta cells of the pancreatic islets of Langerhans." (PMID 30766472, 2019). "By standards of the day, the University received substantial royalties on sales of insulin and used these funds to support both diabetes research and more general university needs." (PMID 30357355, 2019).
diabetes (continued). "The Danish Cancer Registry provided evidence that among cancer patients with pre-existing diabetes, mortality rates were higher on patients receiving insulin." (PMID 30791870, 2019). "Subjects with PDR were older and more often male, had diabetes for longer, were more often insulin users, had lower BMI and lower eGFR as compared with those without DR." (PMID 31751306, 2019). "Here, we present population-based study results for metabolic control, obesity, and hypertension in young people under the age of 25 with T1D treated by intensive insulin therapy, whose diabetes duration was more than 6 months." (PMID 31223626, 2019). "It is reported that disruption of insulin signaling in the moue liver, skeletal muscle or adipose tissue can lead to diabetes." (PMID 31920677, 2019). "Accordingly, monitoring the insulin secretory capacity of pancreatic β cells best predicts future diabetes." (PMID 30293774, 2019). "UCPCR has been reported widely for measurement of endogenous insulin secretion and to distinguish between diabetes subtypes." (PMID 31485449, 2019). "Diabetes is characterized by hyperglycemia and insufficiency in the secretion or action of endogenous insulin." (PMID 30934943, 2019). "According to worldwide diabetes standards, fasting insulin concentration and HOMA-IR assessment matter in AD and should be included to prevent insulin resistance development connected with T2D." (PMID 31428627, 2019). "In various rodent models for diabetes, anti-diabetic effects of procyanidins have been reported, including their roles in insulin secretion and sensitivity, food intake, obesity, and inflammatory and oxidative responses." (PMID 31440258, 2019). "Type 1 diabetes involves about 5% to 10% of diabetes patients and is followed by a degenerative autoimmune reaction in β-cells of pancreatic Langerhans, leading to destruction of insulin production." (PMID 31406275, 2019). "The control of postprandial glucose and insulin levels is critical not only for patients with diabetes but also for healthy people in order to prevent glucose intolerance and insulin resistance cycling response." (PMID 31509979, 2019). "Type 2 diabetes mellitus is well characterized by insulin resistance, often related to obesity, and impaired insulin secretion that eventually result in hyperglycemia and its associated complications." (PMID 30941040, 2019). "Insulin resistance sets the stage for progression to diabetes by increasing the demand on pancreatic beta cells to produce insulin, eventually exhausting the insulin supply." (PMID 30873501, 2019). "Clinicians should be aware that patients progressing to insulin within 3 years of diabetes diagnosis have a high likelihood of having type 1 diabetes, regardless of initial diagnosis." (PMID 30969375, 2019). "Physicians including internists, intensivists and emergency physicians should all be aware of EDKA as a potential complication of diabetes therapy, especially in contexts of emergent surgery or discontinuation of insulin." (PMID 31259114, 2019). "Taken together, these results confirmed that neurotrophic support is necessary to prevent diabetes because it ameliorates glucose balance and improves insulin sensitivity." (PMID 31341469, 2019). "Diabetes and insulin self-administration education should be imparted by health professionals at each follow-up visit." (PMID 31915711, 2019). "People with longer duration of diabetes prefer to recommend insulin to others having statistical significance of (p-value 0.000) because of potential benefits of good glycemic control." (PMID 30881393, 2019). "Insulin levels change in the context of diabetes and it is now established that insulin signals in immune cells modulate their function." (PMID 31244863, 2019). "Diabetes is a chronic disease, and metabolic factors affecting brain metabolisms, such as serum glucose, insulin, and glucagon, are altered according to disease progression." (PMID 31675964, 2019).
diabetes (continued). "In diabetes mellitus type 1 (T1DM) theautoimmune destruction of pancreatic beta cells resultsin insufficient insulin secretion." (PMID 30825290, 2019). "For example, the proportion of patients with oedema was much higher in patients with insulin‐treated diabetes than in the other two groups (64%, 54%, and 48%, respectively)." (PMID 31271255, 2019). "Diabetes is a complex metabolic disorder that is characterized by hyperglycemia due to insulin insufficiency and/or insulin dysfunction." (PMID 30800211, 2019). "Our findings established PPARα-responsive miR-15b as a critical regulator of hepatic insulin signaling, thus serving as a new potential therapeutic target for diabetes." (PMID 30949394, 2019). "When the insulin system becomes faulty, blood sugar levels become too high, which can lead to diabetes." (PMID 30747102, 2019). "The treatment of diabetes and its complications usually focus on insulin, angiotensin-converting enzyme inhibitor and angiotensin receptor blocker due to their approved efficacy in clinical and animal researches." (PMID 31362740, 2019). "Optimal type 1 diabetes mellitus (T1D) care requires lifelong appropriate insulin treatment that can be provided by either multiple daily injections (MDI) of insulin or by a continuous subcutaneous insulin infusion (CSII) pump." (PMID 31685014, 2019). "The effects of the PG treatment on diabetes were evaluated through hematological and biochemical analysis including ELISA assays for insulin and glycated haemoglobin A1c (HBA1c) before and after PG extract was supplied." (PMID 31231500, 2019). "Insulin therapy partially reversed the damage induced by diabetes on the structural properties of the bone and mitigated the reductions in the mechanical properties of the bone." (PMID 31038563, 2019). "Inhibition of Hsp90β isoform has been shown to improve glucose tolerance and insulin sensitivity in murine diabetes models." (PMID 31885746, 2019). "In this study, we found that treatment with fucoidan for 5 weeks significantly increased insulin levels, improved the glucose tolerance, delayed the onset and decreased the development of diabetes by 26 weeks of age in NOD mice." (PMID 31889967, 2019). "Treatment of diabetes mellitus involves diet control, exercise and the use of insulin and/or oral hypoglycemic drugs." (PMID 31212585, 2019). "Patients with diabetes who received insulin were younger (68 years) and less often of white race (83%), compared to patients with diabetes not on insulin (70 years and 85%, respectively) or patients without diabetes (71 years and 92%, respectively)." (PMID 31271255, 2019). "Insulin resistance (IR) is a physiological condition related to type 2 diabetes mellitus (T2DM) and obesity, which is associated with high blood insulin and glucose." (PMID 31534973, 2019). "Approximately 7 of every 10 participants were on metformin before insulin initiation, and metformin was the most common therapeutic class (N = 53,017, 72.7%), while less than half of participants used other non-insulin diabetes medication classes." (PMID 30759121, 2019). "Diabetes mellitus is characterized by the increased levels of glucose in the blood or hyperglycemia due to abnormalities in insulin secretion or insulin action, or both." (PMID 31427896, 2019). "Diabetes mellitus (DM) is a complex metabolic disorder caused by genetic and/or environmental factors, and it is characterized by sustained hyperglycemia due to deficient insulin secretion in islets or insulin resistance in the peripheral target organs." (PMID 31514313, 2019). "For example, the insulin signaling pathway in KEGG draws from experimental evidence from different diseases including diabetes, cancer, and hamartoma syndrome." (PMID 31604427, 2019). "Type 2 diabetes mellitus (T2DM) is defined by chronic hyperglycemia and defective metabolism of carbohydrates, lipids, and proteins caused by inadequate insulin secretion and/or insulin action." (PMID 31470851, 2019).
diabetes (continued). "TZDs, such as rosiglitazone and pioglitazone, are potent insulin sensitizers for the treatment of type 2 diabetes mellitus." (PMID 31581474, 2019). "Other interventions for early diabetes include strongly agonistic insulin mimotopes, which have been used in humanized mice to tolerize and treat diabetes." (PMID 31695065, 2019). "The purpose of opening the additional exclusive diabetes afternoon clinic was to devote more time during the service to chronic patients who had uncontrolled and complicated diabetes as well as patients on insulin." (PMID 30621675, 2019). "Islet transplantation is a β-cell replacement therapy that has the potential to make type 1 diabetes mellitus (T1DM) patients free of insulin injections." (PMID 31822724, 2019). "Another previous study proposed that inadequate knowledge about diabetes contributes to insulin errors." (PMID 30936779, 2019). "Type 2 DM was the most common type of diabetes (n = 786, 87.8%), and most of the patients used combination therapy of oral antidiabetic medications and insulin (n = 321, 35.9%)." (PMID 31647820, 2019). "Meanwhile, β-cell dysfunction following insulin secretion has been found to decrease in patients with type 2 diabetes mellitus." (PMID 31018587, 2019). "This might be because, as the association often provides continuous DM-related education, patients may have a better knowledge of insulin therapy, knowledge of diabetes mellitus and have favorable attitude towards insulin." (PMID 31692777, 2019). "First, we divided the cohort into two groups, those receiving insulin and those receiving anti-diabetes treatment other than insulin." (PMID 31046673, 2019). "Physicians and patients play a role in the decision to start insulin, and patients with uncontrolled diabetes, in particular, will require increased insulin usage in the future." (PMID 31885556, 2019). "And further increases in the requirement of pancreatic insulin secretion eventually lead to diabetes." (PMID 31915709, 2019). "The analysis was based on data collected only from females of Pima Indian decent, and contained plasma glucose and serum insulin (which are key indicators of diabetes) as features for prediction." (PMID 31694707, 2019). "Insulin resistance (IR), known to reduce the response to insulin action, develops with obesity leading to type 2 diabetes mellitus (T2DM)." (PMID 31250990, 2019). "Ultimately, incorporating these structural motifs into DOI or other B chain-truncated analogs of human insulin is likely to lead to the generation of new classes of monomeric insulin analogs for the treatment of diabetes." (PMID 30747102, 2019). "His diabetes prior to the transplant has been well controlled with multiple insulin injections using dilute lispro insulin and NPH in the morning and insulin glargine in the evening, with an A1c = 7%." (PMID 31788263, 2019). "Type 2 diabetes mellitus (T2DM) is the most common form of diabetes and results from the body’s ineffective use of insulin." (PMID 30678216, 2019). "Findings will help to guide future research to determine if instruction in mindfulness, an evidence-based stress management skillset, is efficacious in improving insulin and glucose metabolism when integrated with standard diabetes education." (PMID 31511777, 2019). "The study inclusion and exclusion criteria, while allowing for a broad array of participation, did eliminate individuals who had specific obesity-related comorbidities, such as diabetes that required insulin." (PMID 31743365, 2019). "Diabetes mellitus (DM) is a progressive and chronic metabolic disorder characterized by hyperglycemia arising from impaired insulin levels, insulin sensitivity, and/or insulin action, leading to increased oxidative stress." (PMID 31282614, 2019). "In recent years, the problem of lean type 2 diabetes mellitus (type 2 DM) has become a focus of attention in that impaired insulin secretion is involved in the onset of type 2 DM." (PMID 31275653, 2019).
diabetes (continued). "Antidiabetic medication such as an oral hypoglycemic agent plus insulin is used as an active regimen for blood glucose control to prevent diabetes and diabetes complications; however, drug therapy alone is not sufficiently effective." (PMID 30998218, 2019). "Non-obese diabetic (NOD) mice strain is an autoreactive CD8+ T cell-driven disease model, which developed diabetes spontaneously due to the destruction of the pancreatic insulin-producing beta cells." (PMID 30934882, 2019). "In the last decade, there have been significant breakthroughs in the development of diabetes technology that improves insulin delivery, such as continuous subcutaneous insulin infusion (CSII) pump therapy." (PMID 31507338, 2019). "At the moment, only four peptides isolated from spiders, scorpion and conus block the potassium channel and increase insulin secretion; therefore, these toxins show another possible therapeutic pathway by which to treat diabetes, besides KATP channels." (PMID 31091684, 2019). "Slightly over half (57%) of the study participants indicated normal blood sugar and the rest (34%) reported diabetes of whom slightly above half took oral medication and slightly less than half were insulin‐dependent." (PMID 31367409, 2019). "Type 1 diabetes mellitus (T1D) is a pathology emerging from the selective elimination of pancreatic insulin-producing beta cells mediated by an autoimmune defect." (PMID 31561568, 2019). "There are studies with animal streptozotocin-induced diabetes where treatment with insulin restores nNOS synthesis." (PMID 30987291, 2019). "In women with normal glucose tolerance, the changes in insulin sensitivity are overcome by a sufficient increase in insulin production by pancreatic beta cells, but in women with diabetes, endogenous insulin secretion is insufficient during pregnancy." (PMID 31828161, 2019). "In 26.8% patients, this emergency was the first presentation of diabetes and 22.5% patients had taken inadequate dose/missed their insulin dose." (PMID 31372327, 2019). "On the other hand, T2DM, also known as non-insulin-dependent diabetes, results from the body’s ineffective use of insulin and hyperglycemia and accounts for the vast majority of people with diabetes around the world." (PMID 31575072, 2019). "In their study, abnormal MPI was found to be correlated well with diabetes duration, insulin therapy, diabetic nephropathy and neuropathy." (PMID 31237136, 2019). "It is noteworthy that the optimal solution is close to the standard insulin based therapy for glucose regulation in diabetics." (PMID 30893335, 2019). "Patients with type 2 diabetes mellitus have defective insulin secretion and/or inadequate ability to utilise insulin produced by the body." (PMID 31847918, 2019). "Striatal dopamine also can regulate systemic glucose metabolism; and DBS in patients with diabetes results in increased insulin production and enhanced glycemic control following stimulation of the basal ganglia." (PMID 31388355, 2019). "Community-dwelling people with diabetes must check their own blood glucose levels and administer insulin themselves." (PMID 30974788, 2019). "The diabetes treatment plan was changed to human biosynthetic insulin injection (16 units per day), sitagliptin (50 mg per day), and voglibose (0.3–0.2 mg twice a day)." (PMID 31883520, 2019). "Concerning NCDs, the least affordable is insulin therapy for diabetes patients which can consume up to 15.6 days’ worth of wages at a retail pharmacy." (PMID 30753219, 2019). "On the contrary, failure of compensatory hypersecretion, or even a decrease in insulin secretion, led to a status of impaired glucose tolerance or even overt diabetes." (PMID 31514320, 2019). "In particular insulin treated diabetes is an independent and strong predictor of late and repeat coronary revascularization." (PMID 30832662, 2019).